BANK1 (B cell scaffold protein with ankyrin repeats 1)
Description:
Involved in B-cell receptor (BCR)-induced Ca(2+) mobilization from intracellular stores. Promotes Lyn-mediated phosphorylation of IP3 receptors 1 and 2.
Synonyms: BANK; FLJ20706
Tractability: Antibody: the Human Protein Atlas places it where antibodies can reach. PROTAC: ubiquitination databases record sites on it; its protein half-life has been measured.
Gene: Protein-coding gene on chromosome 4 (101,411,286 to 102,074,812, forward strand). Ensembl gene ENSG00000153064.
Subcellular location (Human Protein Atlas): Cytosol; Plasma membrane; Nucleoplasm
Gene Ontology:
Molecular function: phospholipase binding; protease binding; protein binding; protein tyrosine kinase binding; signaling adaptor activity; signaling receptor binding
Biological process: B cell activation; positive regulation of peptidyl-tyrosine phosphorylation; B cell receptor signaling pathway; negative regulation of B cell activation; negative regulation of phosphatidylinositol 3-kinase/protein kinase B signal transduction; regulation of immune system process; regulation of protein metabolic process; signal transduction
Cellular component: perinuclear region of cytoplasm
Genetic constraint (gnomAD): Loss-of-function variants: 62 observed, 66.29 expected, observed/expected ratio (o/e) 0.94, 90% interval 0.76 to 1.16. The upper end of that interval is the gene's LOEUF score, 1.16, which puts it in group 5 of 6, group 1 being the genes least tolerant of losing a copy. Missense variants: 813 observed, 774.94 expected, observed/expected ratio (o/e) 1.05, 90% interval 0.99 to 1.11. Synonymous variants: 279 observed, 257.93 expected, observed/expected ratio (o/e) 1.08, 90% interval 0.98 to 1.19.
Homologues: Orthologues: chimpanzee BANK1 (98% identical), macaque BANK1 (93% identical), rabbit BANK1 (76% identical), dog BANK1 (75% identical), pig BANK1 (74% identical), mouse Bank1 (66% identical), rat Bank1 (66% identical), tropical clawed frog bank1 (35% identical), Drosophila melanogaster stumps (17% identical). Paralogues in human: PIK3AP1 (25% identical).
Diseases named in the same sentence as BANK1 in open-access papers:
BANK1 is named in the same sentence as 57 diseases in open-access papers, as found by Europe PMC text mining. Sharing a sentence is not in itself a finding about the gene and the disease. The quoted sentences say what the papers report.
systemic lupus erythematosus (19 papers, 2009 to 2025). An autoimmune multi-organ disease typically associated with vasculopathy and autoantibody production. "The changes in taxonomic relative abundance were also observed in TLR7Tg mice when compared with TLR7Tg Bank1 deficient mice, but the changes observed in each lupus model were different." (PMID 40761803, 2025). "In our lupus model mediated by TLR7-signaling, the deficiency in Bank1 gene particularly allowed an increase in the abundance of P. distasonis during lupus inflammation development and P. distasonis was proved to exert anti-inflammatory effects." (PMID 40761803, 2025). "In vitro stimulation either with P. distasonis or via TLR9 allowed for the differentiation of IL-10 producing B cells which, in vivo, differentially accumulated in the Peyer ́s patches of Bank1-deficient lupus mice." (PMID 40761803, 2025). "In our experiments, supplementing P. distasonis in the IMQ-induced WT mice, phenocopied the diminished lupus severity observed in Bank1-deficient mice." (PMID 40761803, 2025). "The effects of Bank1 deficiency on various lupus phenotypes in the TLR7.tg6 model, by 32 weeks of age, and the IMQ-induced model, by 20 weeks of age, were analyzed." (PMID 39163122, 2024). "We therefore confirm the increase of ABCs in the 3 lupus strains and how Bank1 deficiency reduces this population of cells." (PMID 39163122, 2024). "The darkolivegreen module was enriched for SNP-adjacent protein-coding genes, was enriched for a B cell signature, and included SNP-adjacent B cell genes such as BANK1, which has been associated with systemic lupus erythematosus." (PMID 38329124, 2024). "In both lupus models, mice deficient in Bank1 showed a significantly reduced proportion of IgG+ ABCs compared with TLR7.tg6 and IMQ-treated WT mice." (PMID 39163122, 2024). "Among these genes, POMC produces peptides involved in anti-inflammatory actions, BANK1 is associated with systemic lupus erythematosus, and MAST3 and AHSA2 are associated with IBD, corroborating the role of immunity-related genes in shaping gut microbiota." (PMID 37081571, 2023). "BANK1 was mainly associated with autoimmune diseases especially with systemic lupus erythematosus (SLE)." (PMID 33815360, 2021). "BANK1 is required for the production of various proinflammatory cytokines and has been associated with systemic lupus erythematosus (SLE), systemic sclerosis, and rheumatoid arthritis in multipole genome-wide association studies." (PMID 32198144, 2020). "We demonstrate the functional consequences of rare and low frequency missense variants in the interacting proteins BLK and BANK1, which are present alone, or in combination, in a substantial proportion of lupus patients." (PMID 31101814, 2019). "The B cell adaptor with the ankyrin repeats 1 (BANK1) gene is a susceptibility gene for the systemic autoimmune diseases of systemic lupus erythematosus, rheumatoid arthritis, and systemic sclerosis." (PMID 30096841, 2018). "BANK1 single nucleotide polymorphisms contribute to autoimmune disease susceptibility in diseases such as systemic lupus erythematosus (SLE) and RA, both of which have B cells involved in their pathogenesis and progress." (PMID 29370826, 2018). "In some studies, functional variants of BANK1 are associated with autoimmune diseases such as systemic lupus erythematosus (SLE) and RA." (PMID 29370826, 2018). "To determine if deficiency of Bank1 had any effects on disease phenotypes and disease progression, we began by analyzing the effects of Bank1 deficiency on major lupus phenotypes." (PMID 27228057, 2016). "Several inflammatory, autoimmune diseases have been genetically associated with the human BANK1 gene in genome-wide association studies, such as systemic lupus erythematosus (SLE), systemic sclerosis and rheumatoid arthritis." (PMID 27228057, 2016).
systemic lupus erythematosus (continued). "BANK1 has been convincingly identified as a risk factor for the autoimmune diseases systemic lupus erythematosus (SLE) and systemic sclerosis (SSc)." (PMID 23646104, 2013). "A common functional missense variant in the B-cell scaffold protein BANK1 was shown to be in high LD with a common intronic variant that alters splicing, and both variants were strongly associated with systemic lupus erythematosus." (PMID 22174694, 2011). "Implications of Bank1 deficiency have also been proved in murine models of lupus." (PMID 40761803, 2025). "Thus, Bank1 deficiency reduces the generation and expansion of IgG+ and IgG2c+ ABCs in our lupus models." (PMID 39163122, 2024). "Functional variant and polymorphism of BANK1 are associated with susceptibility to autoimmune diseases, such as systemic lupus erythematosus, rheumatoid arthritis, diffuse cutaneous systemic sclerosis, and primary Sjogren's syndrome, suggesting an important role of BANK1 in autoimmune diseases." (PMID 36277750, 2022). "The gene for BANK1, located in chromosome 4, has been found to contain genetic variants that are associated with several autoimmune diseases and also other complex phenotypes, in particular, with systemic lupus erythematosus." (PMID 34066164, 2021). "Thus, the increased expression of the FL BANK1 isoform should increase the risk for systemic lupus erythematosus (SLE)." (PMID 30096841, 2018). "Fcgr2b may play a role in the maintenance of peripheral tolerance and its polymorphism is, like that of BANK-1, significantly associated with systemic lupus erythematosus (SLE)." (PMID 24427159, 2013). "Additionally, the Bank1 deficiency and the proliferation of P. distasonis, allowed the differential translocation of commensals, restraining that of Lactobacillus salivarius, which has been positively correlated with the disease activity in lupus patients." (PMID 40761803, 2025). "A genome-wide association study identified BANK1 as a susceptibility gene for systemic lupus erythematosus (SLE)." (PMID 34066164, 2021). "We aimed at investigating how Bank1 regulates the intestinal immune response in the context of lupus development previously observed to be immunomodulated by its absence." (PMID 40761803, 2025). "During the analysis of gut inflammation parameters in lupus, Bank1-/- mice microbiota showed a persistent increase of P. distasonis within the microbial community that correlated with dampened lupus severity." (PMID 40761803, 2025). "To study the role of Bank1 in the intestinal lupus pathology, we used two TLR7-dependent lupus models, the inducible (IMQ-mediated) and the spontaneous TLR7 transgenic lupus models." (PMID 40761803, 2025). "Because P. distasonis and B. acidifaciens were differentially more abundant in Bank1-/- mice upon lupus development, we assessed their immunoregulatory capacity." (PMID 40761803, 2025). "The evaluation of renal damage revealed that IMQ-treated Bank1-/- lupus mice experienced a reduction in glomerulonephritis compared with IMQ-treated WT controls." (PMID 40761803, 2025). "The B-cell scaffold protein with ankyrin repeats 1 (BANK1), is a well-known susceptibility gene for lupus, particularly associated in African Americans." (PMID 40761803, 2025). "The cecal content of IMQ-induced WT mice receiving P. distasonis was enriched in UMP, and the cecal content of Bank1-/- mice with lupus was enriched in inosine and UMP." (PMID 40761803, 2025). "Here, we investigated the involvement of Bank1 in the gut mucosal B cell response to commensals in a murine model of lupus." (PMID 40761803, 2025). "Bank1 deficiency restores the cellular phenotypes of splenic B-lymphocyte populations TLR7.tg6 and IMQ-treated lupus-prone mice." (PMID 39163122, 2024). "It is worth mentioning that a recent study conducted a scRNA-Seq study in peripheral blood mononuclear cells from patients with lupus, revealing a distinct cluster of B cells characterized by elevated BANK1 expression." (PMID 39163122, 2024).
systemic lupus erythematosus (continued). "In its absence, ABCs exhibited an antiinflammatory gene expression profile, while being proinflammatory in Bank1-sufficient lupus-prone mice." (PMID 39163122, 2024). "The importance of the gene B cell scaffold with ankyrin repeats (BANK1) was gained due to the genetic studies on systemic lupus erythematosus and other diseases that followed." (PMID 34066164, 2021). "Given that B. acidifaciens and P. distasonis were among the most abundant species in the gut of Bank1-/- mice with lupus, we elected to further validate the microbial signature associated with the absence of Bank1 in lupus by means of a Wilcoxon test and recursive feature elimination (RFE)." (PMID 40761803, 2025). "Furthermore, deficiency of Bank1 in TLR7-transgenic (TLR7Tg) mice leads to a reduction in age-associated B cells (ABCs) and in an IFN-stimulated gene expressing B cell population, otherwise, increased in the TLR7Tg.Bank1+/+ lupus mice." (PMID 40761803, 2025). "Furthermore, the ANCOM analysis showed that P. distasonis and B. acidifaciens were common bacteria in the gut of Bank1-/- mice with lupus both in the IMQ-treated and in the TLR7Tg.Bank1-/- mice." (PMID 40761803, 2025). "These two phenomena might contribute to the reduction of intestinal permeability observed in Bank1-/- mice with lupus." (PMID 40761803, 2025). "Furthermore, the proportion of IgG2c+ ABCs was also significantly decreased in TLR7.tg6.Bank1–/– and IMQ-treated Bank1–/– mice compared with Bank1-sufficient lupus-prone mice." (PMID 39163122, 2024). "Also, the increased percentage of CD138+ plasma cells (PCs) in both lupus models, compared with healthy control and untreated mice, was reduced in Bank1–/– mice." (PMID 39163122, 2024). "Bank1 deficiency decreases autoantibody production in TLR7.tg6 and IMQ-treated lupus-prone mice." (PMID 39163122, 2024). "Furthermore, alternate splicing of critical regulatory genes has been identified to associate with risk of other autoimmune diseases, such as alternate splicing of BANK1 in Systemic Lupus Erythematosus." (PMID 19401759, 2009). "Also, Bank1 deficiency normalized the presence of naive B cells, which were nearly absent in lupus-prone mice." (PMID 39163122, 2024). "Furthermore, the co-segregation of variants in BANK1 and BLK in two families suggests that sporadic lupus may occur upon inheritance or de novo occurrence of two or more rare variants with strong effects that act together to cause disease." (PMID 31101814, 2019). "The B-cell scaffold protein with ankyrin repeats (BANK1) regulates Toll-like receptor-7 (TLR7) signaling in B cells and its absence ameliorates lupus." (PMID 40761803, 2025). "In lupus mice, the analysis of intestinal IgA production showed that IMQ-treated Bank1-/- mice had similar levels of fecal free IgA as IMQ-treated WT controls." (PMID 40761803, 2025). "Furthermore, the amelioration of lupus gut pathology in mice lacking Bank1 was linked to the increase of Parabacteroides distasonis that when vertically transmitted or orally administered, as emerging probiotic, reduced disease severity and repaired signs of distorted intestinal permeability." (PMID 40761803, 2025). "The size of CL1 was augmented in lupus-prone mice compared with WT mice and was slightly increased in TLR7.tg6 compared with TLR7.tg6.Bank1–/– mice." (PMID 39163122, 2024). "In TLR7.tg6.Bank1–/– and IMQ-treated Bank1–/– mice, the frequency of ABCs was significantly reduced compared with Bank1-sufficient lupus-prone mice." (PMID 39163122, 2024). "BANK1 and BLK belong to the pleiotropic autoimmune genes; recently, epistasis between BANK1 and BLK was detected in systemic lupus erythematosus." (PMID 23646104, 2013). "Particularly, we found that the absence of Bank1 allowed the increase of P. distasonis abundance during lupus development in both the IMQ-induced model and the TLR7Tg model." (PMID 40761803, 2025).
systemic lupus erythematosus (continued). "Additionally, to confirm the role of Bank1, through TLR7-dependent pathway, in the control of the ABC population, we evaluated the percentage of ABCs in a third lupus model, the B6.Sle1." (PMID 39163122, 2024). "ABCs are reduced in the absence of Bank1 in TLR7.tg6 and IMQ-treated lupus-prone mice." (PMID 39163122, 2024).
autoimmune disease (15 papers, 2009 to 2025). A disorder resulting from loss of function or tissue destruction of an organ or multiple organs, arising from humoral or cellular immune responses of the individual to their own tissue constituents. "STX8 and YES1 are implicated in T-cell activation, MAP4K5, RRM2B, FOXO1, ERBB2IP and INPPL1 can promote inflammation and KIM1, MVK and BANK1 have been associated with autoimmune diseases." (PMID 40247373, 2025). "The B-cell adaptor protein with ankyrin repeats (BANK1) has been consistently associated with the autoimmune diseases such as SLE and systemic sclerosis BANK1 acts in the B-cell signaling pathway but lacks enzymatic activity." (PMID 23555801, 2013). "Similarly, the branchpoint-site single-nucleotide polymorphisms rs17266594 and rs10516487 in the B cell scaffold protein with ankyrin repeats 1 (BANK1) gene have been testified to be associated with various autoimmune diseases including SLE, RA, and SSc." (PMID 33344450, 2020). "However, only a few studies have verified the roles of the BANK1 protein in autoimmune diseases and immune-associated diseases." (PMID 29370826, 2018). "Several autoimmune diseases report associations with BANK1, including systemic sclerosis, rheumatoid arthritis, autoimmune thyroid disease, and germinal center formation in Sjögren’s syndrome minor salivary glands, suggesting BANK1 as a general autoimmunity susceptibility gene." (PMID 34127828, 2021). "BANK1 (B Cell Scaffold Protein With Ankyrin Repeats 1) is a B-cell specific scaffold protein that is likely involved in autoimmune diseases." (PMID 40158147, 2025). "Most of articles on BANK1 report genetic studies showing the importance of BANK1 in autoimmune diseases." (PMID 33815360, 2021). "Combined with the control of the nuclear translocation of IRF7, the modulation of STAT1 transcription and phosphorylation, Bank1 contributes to IgG production during development of autoimmune disease." (PMID 27228057, 2016). "The BANK1 gene encoding the B-cell scaffold protein with ankyrin repeats was previously found associated with human SLE and other autoimmune diseases in distinct populations and ethnic groups." (PMID 26057447, 2015). "Together, our results outline a new signaling pathway in B-lymphocytes including the autoimmunity associated genes BANK1, PLCg2 and BLK and they fill a gap in our understanding of the mechanistic relation between associated alleles in human autoimmune diseases and B-cell physiology in particular." (PMID 23555801, 2013). "BANK1 and BLK have been associated to human autoimmune diseases." (PMID 23555801, 2013).
rheumatoid arthritis (9 papers, 2013 to 2022). A chronic, systemic autoimmune disorder characterized by inflammation in the synovial membranes and articular surfaces. "Functional variants of the B cell gene, B cell scaffold protein with ankyrin repeats 1 (BANK1) contribute to rheumatoid arthritis (RA) susceptibility, but their influences on B cell responses are unclear." (PMID 29370826, 2018). "Epistasis between BANK1 rs3733197 and BLK rs13277113 in rheumatoid arthritis: association of BANK rs3733197 G allele and BLK rs13277113 genotypes." (PMID 23646104, 2013). "Although BLK has been reproducibly identified as a risk factor in rheumatoid arthritis (RA), reports are conflicting about the contribution of BANK1 to RA susceptibility." (PMID 23646104, 2013). "Of note, the lack of clinical and laboratory information (bone erosions, rheumatoid nodules, autoantibodies such as anti-CCPs, rheumatoid factor) as well as the absence of mRNA or protein expression studies to correlate with the four BLK and BANK1 variants studied, are some limitations of our study." (PMID 32153635, 2020).